IFNG (interferon gamma)
Diseases named in the same sentence as IFNG in open-access papers (continued):
Sharing a sentence is not in itself a finding about the gene and the disease.
colitis (continued). "CCR8 signaling protects mice against acute intestinal damage through the action of a subgroup of IFNγ-producing ILCs in a DSS mouse model of colitis; however, it remains to be determined whether these cells are proper ILC2s, ILC1s or Tbet+ exILC3s." (PMID 34299236, 2021). "Again, colitis induction depended on the presence of microbiota and TNFα/IFNγ signaling." (PMID 34188111, 2021). "Rather than rendering the mice vulnerable to C. rodentium, mice treated with M(IL4)s showed enhanced protection against infection and less colonic histopathology that correlated with reduced mRNA expression of IL-22, IL-17 and IFNγ, hallmarks of C. rodentium-colitis." (PMID 34691050, 2021). "Moreover, we observed enhanced expression of IL-17A, IFNγ and TNFα in colon tissues from the colitis mice (DSS-treated) given the EBV DNA compared to the other groups." (PMID 34210024, 2021). "For example, mice with an IFNγ gene ablation are protected against DSS-induced colitis." (PMID 33513946, 2021). "Thus, indirubin ameliorates DSS-induced colitis by suppressing the expression of colonic TNFα, IFNγ, and IL-2 and upregulating IL-10." (PMID 32855621, 2020). "However, in BALB/c mice fed a high-fat, high-sugar diet, only low-dose ALA supplementation (150 mg/kg vs. 300 mg/kg) was protective against TNBS-colitis resulting in significantly lower colonic IL-1, IFNγ, IL-4 and IL-2 cytokine production." (PMID 33603741, 2020). "Additionally, IL-23-responsive ILCs can contribute to chronic intestinal inflammation in H. hepaticus innate colitis model through production of inflammatory cytokines, including IFNγ." (PMID 33488580, 2020). "In contrast, upon adoptive transfer and induction of colitis the subset distribution of NCOR1-deficient CD4+ T cells is changed and hence the percentage of IFNγ+ Th cells might be reduced." (PMID 32318068, 2020). "Both frequency and total cell number of IFNγ-producing ILC1s and ILC3s were significantly reduced in IL-23-/- mice after C. jejuni infection, demonstrating that IL-23 is important to promote IFNγ-production by these ILCs during C. jejuni-induced colitis." (PMID 33488580, 2020). "Colitis increased secretion of IFNγ and of IL-6 and tended to increase the secretion of TNFα." (PMID 32156075, 2020). "TNBS-induced colitis included the secretion of various pro-inflammatory cytokines, such as IL-12, which played an important role in differentiation of T lymphocytes into Th1 effector cells that synthesize interferon gamma (IFN-γ) and TNF-α." (PMID 31546840, 2019). "However, there are some reports which suggest an anti-inflammatory role of IFNγ in the mouse model of colitis as well." (PMID 31488616, 2019). "Interestingly, apart from toxin-induced cytotoxicity, C. difficile infection leads to the activation of a cascade of mucosal pro-inflammatory cytokines, including IFNγ, TNFα, and IL1β, that result in recurrent colitis or ileitis." (PMID 30948494, 2019). "Single transfer of either Rorγt deficient naïve CD4 CD45RBhi or IFNγ-deficient Th17 T cells did not induce disease, pointing to a principal role of IFNγ for colitis development." (PMID 29416538, 2018). "Taken together, while IFNγ has been demonstrated to be highly expressed in CD patients as well as in several animal models of colitis, it remains controversial whether IFNγ plays an indispensable role in the pathogenesis of IBD." (PMID 29416538, 2018). "In contrast, when IL17A and IL17F were neutralized in the presence of IFNγ-producing cells, the histopathological assessment revealed severe colitis although the total score was slightly lower in anti-IL17A and IL17F treated mice compared to untreated recipient mice (data not shown)." (PMID 29416538, 2018). "Indeed, IFNγ-producing ieILC1 cells have been shown to contribute to the development of colitis in a murine model of IBD." (PMID 29686665, 2018).
colitis (continued). "In the T cell transfer colitis model, the introduction of PTPN2 deficient CD4+ T cells resulted in an almost 3-fold increase in the frequency of IFNγ producers and a 2-fold increase in the frequency of IFNγ+ IL17+ double producers." (PMID 30429852, 2018). "IFNγ has been shown to be elevated in the colonic mucosa of IBD patients as well as in several animal model of colitis and the beneficial effect of IFNγ neutralizing antibodies in T cell dependent animal models of colitis indicated the importance of this cytokine for colitis induction." (PMID 29416538, 2018). "This transition of Th17 precursors to Th1-like cells was absolutely required for colitis development, as IFNγ-deficient Th17 cells failed to induce intestinal inflammation." (PMID 29416538, 2018). "Similarly, IFNγ-deficient mice were protected from DSS-induced colitis, and in the innate lymphoid cell (ILC) dependent anti-CD40-induced colitis." (PMID 29416538, 2018). "Therefore, it has been proposed that blocking IFNγ should have beneficial effects on the development of colitis." (PMID 29416538, 2018). "In line with this hypothesis, blockade of IFNγ during T cell transfer model of colitis in Scid mice was shown to ameliorate intestinal inflammation." (PMID 29416538, 2018). "Pro-inflammatory Tnf, Ifnγ, Il6 and Il1β mRNA expression levels were increased in colitis." (PMID 30315190, 2018). "Similarly, intraepithelial ILC1 have been demonstrated in patients with Crohn’s disease and have been suggested to contribute as a proinflammatory IFNγ-producing population to the pathology in an anti-CD40-induced colitis model in mice." (PMID 29526762, 2018). "Here, we demonstrated a divergent role of IFNγ in the development of colitis." (PMID 29416538, 2018). "This is consistent with prior work demonstrating IFNγ induction of epithelial cell death such that IFNγ-knockout animals were protected from epithelial damage in vivo in a DSS-colitis model and, in epithelial cell lines, IFNγ inhibited epithelial proliferation by suppressing β-catenin activity." (PMID 29505600, 2018). "As noticed above we observed particularly in DNBS-induced colitis an increase of IL-5, IL-17 and IFNγ in colon tissue of mice treated with LL-pILEMPTY compared to control group and a tendency to decrease IL10 even if the difference is not statistically significant." (PMID 28203226, 2017). "In the present study, CaA could significantly reverse the increase of IL-6, TNFα and IFNγ in DSS colitis mice." (PMID 27177331, 2016). "Administration of rSjcystatin significantly reduced inflammatory parameters and ameliorated the severity of the TNBS-induced colitis through decreasing IFNγ in three organs and lifting the level of IL-4, IL-13, IL-10, and TGF-β in the colon tissues, with uptrending Tregs in the MLN and LPMC." (PMID 26728323, 2016). "Interferon-gamma (IFN-γ), produced by natural killer, natural killer T cells and T cells, is the signature cytokine of T helper (Th) 1 immune responses and it has been involved in the pathogenesis of colitis and Sjögren Syndrome." (PMID 27623073, 2016). "Plasma levels of IL-1β, IL-6, IL-10, IL-17, TNFα, and IFNγ were detected in blood samples from all experimental mice group at two different time points, one corresponding to the acute phase of colitis (day 25), and one at the end of the recovery phase (day 37)." (PMID 26973525, 2016). "In mice, colitis studies revealed not only the presence of Th1/Th17 hybrid cells but also that Th17 cells, initially unable to produce IFNγ, abolish IL-17 production completely and switch on IFNγ (ex-Th17Th1)." (PMID 25339956, 2014). "Development and remission of DSS-induced colitis in mice was determined by weight measurements and histology scores, and by quantification of expression of pro- (IL-1β, IL-6 and IFNγ) and anti-inflammatory (IL-10) cytokines, the chemokine CXCL1 and the inducible nitric oxide synthase." (PMID 24401855, 2014).
colitis (continued). "Also if we determined specifically the percentage of P-lig+ cells among Th1 effector cells identified by IFNγ-expression a drastic increase in the frequency of P-lig+ cells was observed during both, colitis and ileitis, compared to homeostatic conditions." (PMID 23630623, 2013). "However, in the models we have previously used for experimental DSS inducing epithelial injury (i.e., leaky mucosa) resulting in colitis or pathogenic CD4+CD45RBhigh T cell transfer; IFNγ seems to be involved in the pathogenesis of the induced colitis." (PMID 22423982, 2012). "When used to treat colonic inflammation induced by TNBS administration to Balb/c mice, ciprofloxacin effectively protected against development of local signs of colitis and markedly reduced local generation of inflammatory mediators including IL-1β, IL-6, IFNγ and TNFα." (PMID 22046243, 2011). "Further experiments are required to decipher the mechanism, but interferon-gamma–producing Th1 cells have been shown to inhibit motor function in postoperative ileus, and high amount of opioids known for their impact on motility have been observed in colonic T cells from colitis models motility." (PMID 38428588, 2024). "Here, authors characterise the gut immune microenvironment during CPI-colitis by bulk RNA sequencing, single-cell RNA sequencing and flow cytometry, and find that interleukin 23 plays an important role in promoting inflammation via cytotoxic polyfunctional IFNγ-producing lymphocytes." (PMID 37872166, 2023). "In a model of DSS-induced colitis, we could not associate either IFNγ or IL-17A production by cLP ILC2 with loss of CD90 expression." (PMID 37114052, 2023). "Notably, there was an increase in the proportion of infiltrated immune cells (CD45+), CD4+ and CD8+ T cells, macrophages (CD11b+F4/80+), and neutrophils (CD11b+Gr1+) in Smad4−/− mice during colitis compared with those in WT mice, which was accompanied by enhanced IFNγ levels." (PMID 37261975, 2023). "In addition, IFNγ is a key mediator in colitis-irAE, as in arthritis-irAE." (PMID 35413951, 2022). "In addition, IL-6R signaling in T cells is a prerequisite for induction of T cell mediated colitis since its blockade has been shown to abrogate proliferation of CD4+ or CD8+ T cells, IFNγ production and induction of colitis in models of T cell transfer colitis." (PMID 35514976, 2022). "Because we saw an increase in CD4 T cell IFNγ production 24 h-post IL-12 stimulation in vitro, and the T cell transfer model of colitis induces chronic inflammation over several weeks, we hypothesized that Plac8’s impact on CD4 T cell IFNγ may be limited to models of acute inflammation." (PMID 32639988, 2020). "Similarly, only Emmental cheese attenuated IFNγ secretion induced by the DSS-induced colitis." (PMID 32156075, 2020). "We have demonstrated here that the severity of low dose DSS (1.5%)-induced colitis is exacerbated in heterozygous Yeti mice on an NKT cell-deficient background, indicating that iNKT cells are essential for maintaining intestinal homeostasis in the context of IFNγ-mediated inflammation." (PMID 30333822, 2018). "Among the pro-inflammatory cytokines driving intestinal inflammation, interferon gamma (IFNγ) has been shown to be highly expressed in the affected mucosa of CD patients and to be one of the main drivers of intestinal inflammation in distinct animal colitis models." (PMID 29416538, 2018). "Therefore, the nearly normal circulating IFNγ levels and colitis pathology were surprising." (PMID 25781948, 2015). "Another study tested the efficacy of a monoclonal anti-mature IL-18 antibody in DSS colitis mice found that it improved acute and chronic DSS colitis, reduced production of IFNγ and TNFα and ameliorated the epithelial cell barrier." (PMID 40642091, 2025). "Increased colitis severity and stronger T helper 17 (Th17) responses, production of TNF and IFNγ by CD4+ T cells." (PMID 40860650, 2025).
colitis (continued). "In this study, the authors identified a subset of eosinophils (PD-L1+ and CD80+) with single-cell transcriptomics, which are induced by cytokines such as IL-33 and IFNγ and exhibit bactericidal and T cell regulatory functions in DSS-colitis." (PMID 40860650, 2025). "Strains that induced higher levels of the anti-inflammatory cytokine IL-10 and lower levels of pro-inflammatory cytokines such as IL-1β, IL-6, interferon γ (IFNγ), and TNF-α offered protection in induced colitis." (PMID 39767038, 2024). "Colonic mRNA of both ICI-colitis and IBD patients have exhibited an upregulation of the IFNγ, IL-17 effector pathways and TNF compared to healthy colons." (PMID 39247203, 2024). "That males were more prone to inflammation was corroborated at the systemic level in our study, by a lower baseline IFNγ plasma levels and lower levels of CCL2 during colitis than females." (PMID 39613949, 2024). "Interferon gamma and tumor necrosis factor (TNF) alpha play central roles in the pathogenesis of both ICI colitis and UC." (PMID 39336463, 2024). "In BALB/c background mice, CD90- ILC accounted for about a fifth to a third of cLP ILC, and we detected a substantial amount of IFNγ, IL-13 and IL-17A production by these cells in the context of DSS- or dysbiosis-elicited colitis." (PMID 37114052, 2023). "In agreement with our findings, we observed increased expression of IFNG, GZMB CXCR6 and CTLA4 in T cell clusters in with patients with CPI colitis patients in comparison with healthy controls." (PMID 37872166, 2023). "In fact, it was shown that the pasteurized preparation of A. muciniphila resulted in downregulation of inflammatory cytokines such as TNFα, Interferon-γ (IFNγ), IL-1β, IL-6, IL-8 and IL-33 with a marked improvement in DSS-induced colitis." (PMID 37370812, 2023). "CD4-neighbouring SIGLEC8 RNA molecules were also significantly associated with NF-κB (NFKB1) and IFNγ (IFNGR1, STAT1 and IRF1) signalling components, which indicates that the same pathways might drive interactions between A-Eos and CD4+ T cells in mouse and human colitis." (PMID 36509106, 2023). "Administration of IPA attenuates pro-inflammatory (CD4+IFNγ+IL10−) T cells and increases anti-inflammatory (CD4+IFNγ−IL10+) T cells in the colon in a mouse model of colitis." (PMID 37298145, 2023). "These CD90- and CD90low ILC are a significant source of IFNγ, IL-13 and IL-17A upon dysbiosis and dextran sulphate sodium (DSS)-elicited colitis." (PMID 37114052, 2023). "Mice with LF-Colitis and LF-CAC showed a significant increase in plasma IL-1β, IFNγ, and IL-12 levels compared to the LF-Ctr mice, which were reduced in the HF-Colitis and HF-CAC groups compared to their LF group counterparts." (PMID 36768196, 2023). "In ICI colitis, TRM CD8+ cells differentiate into cytotoxic T lymphocytes, capable of releasing interferon-gamma (IFNγ) with consequent damage to the intestinal epithelial barrier." (PMID 37239166, 2023). "We showed that KLPJ-mediated colitis occurred through the caspase-11–mediated release of mature IL18 in the gut epithelial cells, which plays an important role in the induction of IFNγ production, increasing NK cell activity and T-cell proliferation." (PMID 36436756, 2023). "This preclinical model of CPI colitis is shown to be dependent on the composition of the microbiota driven by cytotoxic polyfunctional lymphocytes and reliant on the IL23/IFNγ axis." (PMID 37872166, 2023). "Together our data support the rationale for therapeutic targeting of IFNγ producing, polyfunctional T cells in CPI colitis, including neutralisation of their upstream regulators, such as IL23." (PMID 37872166, 2023). "We identified polyfunctional mucosal CD4+ and CD8+ T cells that co-produce IFNγ, other pro-inflammatory cytokines (e.g. IL22, IL17A) and cytotoxic molecules, including granzyme B, as key effector cells in CPI colitis." (PMID 37872166, 2023).
colitis (continued). "An increased proportion of colonic T cells co-expressing IFNγ granzyme B and perforin was observed in CPI colitis, especially in CD4+ and CD8+ T cells." (PMID 37872166, 2023). "Corylin significantly reduced Ifnγ, Tnf-α, Il-6, Il-1β, Nlrp3, Asc, Pannexin, and Pro-caspase 1 mRNA expression and protein levels in DSS-induced colitis mice." (PMID 35269806, 2022). "CD69−CD103− CD4+ T cells accounted for 11.7% of IFNγ-expressing CD4+ T cells in control mice and 24.8% in DSS-induced colitis." (PMID 35844584, 2022). "We also determined that the mRNA levels of IFNγ and IL-17 on mesenteric lymph nodes were regulated by the oral administration of citropten in a DSS-induced colitis model." (PMID 35889507, 2022). "Albeit IFNγ expression was increased in CD69−CD103− and CD69+CD103+ CD4+ T-cell subsets during DSS-induced colitis, only small percentages of CD69−CD103− CD4+ T cells and CD69+CD103+ CD4+ TRM cells expressed IFNγ." (PMID 35844584, 2022). "In contrast, CD69+CD103+ CD4+ TRM cells only accounted for 2.2% of IFNγ- and 5.1% of IL-17A–expressing CD4+ T cells in control mice, 6.5% of IFNγ- and 3.9% of IL-17A–expressing CD4+ T cells in DSS-induced colitis, respectively." (PMID 35844584, 2022). "Colitis in the dual treated mice (i.e., LF82 + DSS) was accompanied by elevated proinflammatory cytokines in the colonic tissues including IL-17, IFNγ, IL-1β, and IL-6 compared to the mice treated with DSS only." (PMID 35381031, 2022). "Cells were isolated during colitis, stimulated ex vivo with phorbol 12-myristate 13-acetate/ionomycin, then surface stained for CD3/CD4, fixed, stained for intracellular IL-17A and IFNγ and analyzed by FCM." (PMID 34983695, 2022). "The administration of antibiotics inhibited the IL-17A, IL-17F and IFNγ-expressing cells in the LILP of both WT and Rap1KO mice, and prevented the development of colitis, indicating that colitis is developed in microbiota-dependent manner in Rap1KO mice." (PMID 35246619, 2022). "The relative gene expressions of IFNγ, IL4, and STAT6 were significantly higher in the HA group in comparison to all groups with colitis (p < 0.01 for all comparisons with HA, with the exception of IL4: AC vs. HA, p < 0.05)." (PMID 33499240, 2021). "Hence, IFNγ expressing ILC may play a critical role at the onset of colitis." (PMID 34795671, 2021). "Using scRNASeq, we are able to confirm IFNG production in T cells that overlap with the TRM cell zones and that IFNG production is detected in all UC, DCC, and anti–PD-1 colitis (PDC) groups." (PMID 34147519, 2021). "Up-regulation of both IFNG and TNFA signaling pathways was identified in the CD4+ and CD8+ T cells of patients with ICI-colitis, acting on the myeloid cellular compartment." (PMID 34147519, 2021). "We find compelling evidence for up-regulated IFNG signaling in ICI-colitis, more so than TNFA, which is the current target of ICI-colitis rescue therapy." (PMID 34147519, 2021). "We identified innate lymphoid cells as a substantial source of IFNγ at steady state, while other cells like T cells and NK cells dominate more once severe DSS-induced colitis is established." (PMID 34795671, 2021). "Previous data show that IFNγ-mediated STAT1 signalling is a key requirement for intestinal caspase-11 upregulation and activation in IECs during DSS-colitis." (PMID 30538296, 2019). "Adoptive transfer of these MDSCs in mice with colitis, induced by 2,4,6-trinitrobenzenesulfonic acid (TNBS), decreased intestinal inflammation as well as the levels of IFNγ, IL-17 and TNFα." (PMID 31130949, 2019). "There also existed a drastic expansion of interferon γ (IFNγ)-producing CD4+ T helper cells (Th1) cells (CD4+IFNγ+Th1 cells) and NKp46+ IFNγ+ cells in the LP tissues of DSS-mediated colitis and E. coli O160:H7-colonized mice." (PMID 31707260, 2019).